RAG2 (recombination activating 2)
Diseases named in the same sentence as RAG2 in open-access papers (continued):
Sharing a sentence is not in itself a finding about the gene and the disease.
Arthritis (8 papers, 2017 to 2025). Inflammation of a joint. "To further determine the contribution of these ILCs to arthritis development, we attempted to selectively deplete ILCs by anti-Thy1.2 mAb in Thy1.2+Rag2−/− mice that had been transferred with CD4+ T cells from Thy1.1+ congenic SKG mice." (PMID 29802020, 2018). "Transfer of Csf2−/− SKG CD4+ T cells induced histologically evident arthritis in Rag2−/− mice although the arthritis was macroscopically less severe than WT SKG CD4+ T cell transfer." (PMID 29802020, 2018). "Peak arthritis clinical scores were also higher in Rag2−/−/Il2rγ −/− mice than in Rag2−/− mice." (PMID 39967734, 2025). "It has been reported that intraperitoneal injection of β-glucan increases Th17 cells 3–4-folds in the lymph nodes of SKG mice, and that T cells sorted from normal SKG mice possess the potential to cause arthritis in recipient RAG2 KO mice, but not from IL-17A KO SKG mice." (PMID 35879738, 2022). "SKG arthritis is dependent on Th17, because SKG CD4 T cells that were deficient in IL-17 failed to induce arthritis upon adoptive transfer into RAG2-deficient mice, while the induction of arthritis was accelerated by the transfer of IFN-γ-deficient CD4 T cells." (PMID 28753982, 2017). "To further assess the possible contribution of GM-CSF from non-CD4 T cells to arthritis development, we transferred Csf2−/− or WT SKG CD4+ T cells into Rag2−/− or Csf2−/−Rag2−/− mice." (PMID 29802020, 2018). "We adoptively transferred into Rag2-KO mice CD45.1-marked EGFP+ Tregs (CD4+FoxP3EGFP+) isolated from either the spleens or colons of FoxP3EGFP SKG mice together with CD45.2-marked SKG CD4+ effector (CD4+CD25–) peripheral T cells and monitored development of arthritis after injection of mannan." (PMID 33055428, 2020).
eosinophilia (8 papers, 2013 to 2023). "γc deficient mice on a RAG2−/− background still developed significantly higher pulmonary inflammation and eosinophilia." (PMID 23940740, 2013). "Here we report that γc deficient mice developed increased pulmonary inflammation and eosinophilia upon OVA challenge when compared to RAG2−/− mice when provided with OVA-specific T-cells." (PMID 23940740, 2013). "However, the degree of inflammation and eosinophilia in RAG2−/− mice was still significantly lower than that observed in γc deficient mice." (PMID 23940740, 2013). "As in wild type mice, CDG nearly abolished Alt-induced lung eosinophilia and reduced BAL IL-5 (p = 0.0518) in Rag2-/- mice." (PMID 33679760, 2021). "Both γc−/− and γcxRAG2−/− mice developed increased pulmonary inflammation and eosinophilia upon OVA challenge, compared to RAG2−/− mice." (PMID 23940740, 2013). "In particular, neutrophils, macrophages and lymphocytes, but not eosinophils, were increased in BAL fluids of Rag2−/− mice compared with wild-type mice, suggesting that acquired immune cells such as T, B and NKT cells were not essential for FAP-induced airway eosinophilia." (PMID 30575775, 2018).
acute lymphoblastic leukemia (7 papers, 2018 to 2025). Leukemia with an acute onset, characterized by the presence of lymphoblasts in the bone marrow and the peripheral blood. "Finally, the RAG1/RAG2 recombinase, which catalyzes the V(D)J recombination, is a driver of the genetic instability linked to lymphoblastic leukemia." (PMID 33407840, 2021). "Furthermore, we established human acute lymphoblastic leukemia xenograft rat model by intravenously injecting 5.0 × 106 cells/kg of NALM6 cells into Il2rg/Rag2 KO rats." (PMID 39731164, 2024). "To investigate the in vivo relevance of PRL-3’s catalytic and non-catalytic functions, we used a zebrafish model of T-cell Acute Lymphoblastic Leukemia (ALL) driven by rag2:Myc overexpression." (PMID 40463094, 2025). "It is noteworthy that trgc is not expressed in the existing zebrafish T-cell acute lymphoblastic leukemia (T-ALL) model driven by rag2-myc47." (PMID 35504924, 2022). "As the rag2 promoter is transcriptionally active during the development of T-,cells as well as B-cells, it has recently been shown that B-cell acute lymphoblastic leukemia (B-ALL) could also occur in this zebrafish T-ALL model." (PMID 31454991, 2019).
atherosclerosis (7 papers, 2012 to 2023). A disease characterized by the build-up of fatty material and calcium deposition in the arterial wall resulting in partial or complete occlusion of the arterial lumen. "B2 B lymphocyte depletion ameliorated atherosclerosis in ApoE−/− mice whereas its adoptive transfer aggravated atherosclerosis in lymphocyte deficient ApoE−/− Rag-2−/− mice." (PMID 33988232, 2021). "BALB/c mice homozygous for targeted immunological mutations like Rag1-knockout, Rag2-knockout and the Il2rg-knockout are suitable recipients for human hematopoetic stem cells and therefore the study of atherosclerosis in humanized mice." (PMID 27564380, 2016). "In order to evaluate the role of adaptive immunity in the acceleration of atherosclerosis observed in Card9-deficient mice, we backcrossed Apoe-/-Rag2-/- mice with Rag2-/-Card9-/- to generate athero-prone lymphocyte (T, B, NKT)-deficient Apoe-/-Rag2-/-Card9-/- mice." (PMID 37528097, 2023). "The acceleration of atherosclerosis is also observed in Apoe-/-Rag2-/-Card9-/- mice, ruling out a role for the adaptive immune system in the vascular phenotype of Card9 deficient mice." (PMID 37528097, 2023). "A previous study has shown that the elevated NK cells via adoptive transfer doubled atherosclerotic lesion size in ApoE-/-Rag2-/-IL2rg-/- mice, indicating that SnPP can exacerbate atherosclerosis through NK cells." (PMID 35281895, 2022). "However, our findings of increased atherosclerosis in immune-deficient Apoe-/-Rag2-/-Card9-/- mice ruled out the possibility that the acceleration of atherosclerosis in the absence of Card9 was mediated by a modulation of the adaptive immune system." (PMID 37528097, 2023). "Adoptive transfer of telomerase reverse transcriptase–/– Tregs into Rag2–/– ApoE–/– (recombination activating gene 2/apolipoprotein E) double knockout mice demonstrated that telomerase function was not required for the ability of Tregs to protect against atherosclerosis." (PMID 29599138, 2018).
myeloma (7 papers, 1992 to 2023). "To gauge the potential benefit of raising arginine against myeloma growth independently of expected effects on adaptive immunity, we xenotransplanted human myeloma cells subcutaneously into young adult T cell-deficient Rag2–/–γc–/– recipient mice." (PMID 36172163, 2022). "The critical role of PD-1H in myeloma lytic bone lesions was confirmed using a Pd-1h-/- myeloma bone disease mouse model wherein myeloma cells injected into Pd-1h-/-Rag2-/- results in attenuated bone destruction." (PMID 37460553, 2023). "To test the relevance of direct arginine-mediated PC autonomous effects on myeloma growth in vivo, we employed the arginase inhibitor, CB1158 to restore arginine concentration in myeloma xenografts into Rag2–/–γc–/– immunocompromised recipient mice." (PMID 36172163, 2022). "This study generated a double deficient (RAG2–/–MMP-9–/–) mouse and demonstrated significant reductions of myeloma cells in the BM and OC number in the 5TGM1 bearing RAG2–/–MMP-9–/– mouse." (PMID 34163520, 2021). "We therefore explored BMP4 gene therapy in a human‐mouse model of multiple myeloma where humanized bone scaffolds were implanted subcutaneously in RAG2−/− γC−/−mice." (PMID 31956851, 2020). "Since Rag2−/− mice develop myeloma similarly to the C57BL6/KaLwRij strain following 5TGM1-GFP inoculation, we reasoned that if tumor-associated MDSCs derived from Rag2−/− mice would also develop into osteoclasts." (PMID 23173040, 2012). "Data showed that 5TGM1-luc myeloma cells induced extensive lytic lesions and trabecular bone loss in Pd-1hwtRag2-/- but not in Pd-1h-/-Rag2-/- mice with maintenance of overall bone structure." (PMID 37460553, 2023). "To determine whether the Gr-1+/CD11b+cells from myeloma-bearing mice could differentiate into osteoclasts in vivo, we established a murine myeloma mouse model that carried the LacZ transgene in the Rag2−/− immunodeficient background (LacZ;Rag2−/− mice)." (PMID 23173040, 2012). "The 5T model is well-characterized and closely mimics human myeloma, however 5T myeloma cells will only grow in syngeneic C57BL/KaLwRij mice, bg/nu/Xid mice or Rag2−/− mice." (PMID 28241871, 2017). "Stable hybrids between the scid pre-B and the myeloma cells had lost theexpression of RAG-1 and RAG-2 genes, supporting the previous finding of an inhibitorof rearrangement in myeloma cells that acts shortly after fusion." (PMID 1343097, 1992).
Hepatitis (6 papers, 2009 to 2021). Inflammation of the liver. "As expected, CCl4-adminstered RAG2−/− × RORγt−/− mice showed a severer hepatitis compared with CCl4-adminstered RAG-2−/− mice." (PMID 23626860, 2013). "Surprisingly, RAG-2−/− × RORγt−/− mice developed significantly severer CCl4-induced hepatitis compared with RAG-2−/− mice, in accordance with the fact that hepatic ILCs failed to produce IL-22." (PMID 23626860, 2013). "NIF mice spontaneously developed chronic liver inflammation and fibrosis initiated by a transgenic population of NKT cells while 2,4αβNOD.Rag2+/− littermate control mice did not34." (PMID 33311540, 2020).
ulcerative colitis (6 papers, 2013 to 2023). An inflammatory bowel disease involving the mucosal surface of the large intestine and rectum. "The spontaneous ulcerative colitis (TRUC) developing in a DC-dependent manner in T-bet/RAG2 double knockout mice is highly penetrant in BALB/c mice, but less severe in C57BL/6 mice." (PMID 26624014, 2015). "A predominance of ILC3 secreting IL-17A accompanied by few IFN-γ-expressing cells was also described in the Tbx21-/-Rag2-/- ulcerative colitis (TRUC mice) disease model." (PMID 25853847, 2015). "In order to determine whether CD90- and CD90low ILC were associated with a T-bet-expressing ILC subset, we analyzed CD90- and CD90low ILC in Tbx21-/- x Rag2-/- non-ulcerative colitis (TRnUC) mice." (PMID 37114052, 2023).
viral infection (6 papers, 2005 to 2024). "Additionally, Rag2−/− mice exhibited increased susceptibility to viral infection and prolonged weight loss, confirming the importance of T and/or B cells in the immune response against SARS-CoV-2, as the depletion of NK cells did not significantly impact the course of the disease in Rag2−/− mice." (PMID 38675952, 2024). "The immunodeficient Rag2−/− mice were more sensitive to Ad5 viral infection than the immunocompetent mice; when luminescent signals were detected with the BLI method, brain tissue sections showed pathological findings only in the Rag2−/− mice." (PMID 28620164, 2017). "In conclusion, there was a strong relationship between viral infection and pathological tissue injuries in immunodeficient Rag2-/- rats." (PMID 26235050, 2015). "Applying adoptive transfers into Rag2-/- mice, we showed that CD4 T cells support CD8 T cells in controlling virus infection in the lungs." (PMID 30153311, 2018).
pancreatic cancer (5 papers, 2010 to 2023). "Here, we establish an orthotopic porcine model of human pancreatic cancer using RAG2/IL2RG double-knockout immunocompromised pigs and treat the tumors ex vivo and in vivo with histotripsy." (PMID 37596154, 2023). "As seen for PC-3 tumors, KD of ITGB4 in human pancreatic cancer cells (PaCa5061) significantly impaired s.c. xenograft tumor growth in WT Pfp−/−/Rag2−/− mice." (PMID 36932441, 2023). "For tumor engraftment, we have evaluated tumor progression of the following human cancer cell lines in the RAG2/IL2RG knockout pigs: PANC-1 (pancreatic cancer); HepG2 (liver cancer); and U-251 (brain cancer)." (PMID 34478363, 2022). "The established PaCa 5061 cell line and its injection into pfp-/-/rag2-/- mice can be used as a new model for studying various aspects of the biology of human pancreatic cancer and potential treatment approaches for the disease." (PMID 20553613, 2010).
Sepsis (5 papers, 2017 to 2022). Sepsis is defined as life-threatening organ dysfunction caused by a dysregulated host response to infection. "In support of proinflammatory, tissue-damaging properties of mature B2 cell subsets, we found splenectomy similarly protective as B cell deficiency during primary sepsis and reconstitution of Rag2-/- mice with B cells to increase tissue damage." (PMID 36178806, 2022). "LPS-injected Rag2 KO rats developed sepsis as indicated by increased TNFa, IL-6, IL-1b, and IL-10 levels and thrombocytopenia." (PMID 31921873, 2019). "To estimate thymic output after sepsis we used RAG2p-GFP transgenic mice in which the RAG2 promoter drives GFP expression and the GFP signal remains detectable in recent thymic emigrants for approximately three weeks after the RAG gene is no longer expressed." (PMID 30730978, 2019). "If the infected Rag2−/− mice were observed for longer, more severe clinical symptoms such as sepsis might be found." (PMID 36016362, 2022). "More importantly, the innate immune responses in Rag2 KO rats, such as high serum levels of TNFa, IL-1, IL-6, and IL-10, and the development of thrombocytopenia also represent those seen in patients with sepsis." (PMID 31921873, 2019). "In both Rag2-/- and JHT mice, LPS pretreatment did not cause increased blood neutrophils nor a significant accumulation in the PLF during sepsis." (PMID 36178806, 2022).
Granuloma (4 papers, 2015 to 2024). A compact, organized collection of mature mononuclear phagocytes, which may be but is not necessarily accompanied by accessory features such as necrosis. "Autoimmune cytopenia, granuloma, skin cancer, vasculitis, neuropathy, interstitial lung disease, and myopathy were detected in 76.2% of patients with RAG1, and 23.8% of the patients with RAG2 deficiency." (PMID 37724703, 2024). "However, ILCs may also directly affect macrophage behavior and subsequent granuloma formation, because Rag2–/– mice lacking B cells are still capable of generating discrete granulomas, and ILC-KO mice lacking B cells and ILCs form significantly fewer granulomas." (PMID 39225100, 2024).
heart failure (4 papers, 2017 to 2025). Inability of the heart to pump blood at an adequate rate to meet tissue metabolic requirements. "Studies using RAG2/SCID mouse models show that pathways leading to B cell activation play a key role in heart failure and disease progression." (PMID 40360833, 2025). "Mice deficient in Rag2, not having functional B and T cells, were protected from the transition from hypertrophy to heart failure after transverse aortic constriction (TAC)." (PMID 31565659, 2019). "Laroumanie and colleagues reported that mice deficient for the recombination activation gene 2 (Rag2), which do not have B and T cells, were protected from the transition from hypertrophy to heart failure after TAC15." (PMID 29167489, 2017). "Specifically CD4+-T cells appeared to be important since mice deficient for MHC class II molecules, which lack CD4+-T cells were protected from progression into heart failure after TAC similarly to RAG2-deficient mice lacking all T cells and in contrast to CD8-deficient mice lacking CD8+-T cells." (PMID 30498501, 2018). "Animal studies using RAG2-/- SCID mouse models with defective T and B cells demonstrate that pathways leading to the activation of B cells are important players in heart failure and disease progression." (PMID 31565659, 2019). "Mice lacking Rag2, and therefore without functional B and T cells, were protected from the shift from hypertrophy to heart failure following transverse aortic constriction." (PMID 40360833, 2025). "Mice lacking a functional recombination activation gene 2 (Rag2), which do not have B and T cells, were reported to be protected from the transition from hypertrophy to heart failure after TAC." (PMID 30498501, 2018).
hepatocellular carcinoma (4 papers, 2009 to 2021). A malignant tumor that arises from hepatocytes. "For example, CTBP1 is listed by Cancer Resource, and TASP1 is also a drug target, which is used to combat novel diseases whose candidate genes are targeted by HNF4alpha splice variants in hepatocellular carcinomas, as well as PNKP and RAG2." (PMID 28691014, 2017).
HIV-1 infection (4 papers, 2006 to 2013). The type species of lentivirus and the etiologic agent of acquired immunodeficiency syndrome (AIDS). "Small animal models for HIV-1 infection such as Rag2-/-/Il2rg-/- mice and BLT mice have made significant contributions to our understanding of HIV/AIDS pathogenesis." (PMID 24381568, 2013). "One report has shown successful engraftment and HIV-1 infection in C57BL/10 Rag2-/-γc-/- mice engrafted with non-purified human fetal liver cells, although another report has shown an inability to achieve usable engraftment in the related C57BL/6 Rag2-/-γc-/- strain." (PMID 21835012, 2011).
influenza infection (4 papers, 2010 to 2018). "We used depleting antibodies and Rag2−/− mice, and found that adaptive immune responses were dispensable for the influenza-induced recruitment of MCp to the lung." (PMID 30337928, 2018). "Using Rag2-deficient mice, the significance of innate immune cells being induced by the IL-33/ST2 pathway has been shown by intranasal IL-33 injections and influenza infection." (PMID 30337928, 2018). "To determine whether ILC2 can produce IL-5 following influenza infection in vivo, we first analyzed IL-5 production and the contribution of ILC2 as a source of IL-5 in adaptive immune cell deficient, IAV infected Rag2-/- mice since the majority of Thy1.2+ cells in these mice are ILC2." (PMID 24068930, 2013). "Rag2-/- mice have so far only been tested in a secondary influenza infection challenge assay after vaccination but were not studied in a primary infection challenge model." (PMID 20667098, 2010).
skin inflammation (4 papers, 2020 to 2024). "Subsequently, when these Th17 cells were transferred into lymphocyte-deficient Rag2 knockout mice, they induced IL-17-dependent subacute skin inflammation, both histologically and immunologically resembling psoriasis." (PMID 38226171, 2024). "When Dsg3H1-pTh17 cells were transferred into irradiated syngeneic wild-type C57BL/6 mice, they induced dermatitis at a slower rate than in Cd3e KO recipients (which lack endogenous T cells and showed EAD with kinetics similar to Rag2 KO recipients)." (PMID 38226171, 2024). "Among PD-1-expressing cells, T cells were the predominant targets of anti-PD-L1 mAb treatment since PD-L1 blockade did not affect skin inflammation in RAG2-/- mice." (PMID 33584713, 2020).
Splenomegaly (4 papers, 2017 to 2023). Abnormal increased size of the spleen. "In contrast to infection of immunocompetent B6 mice, infection in B6.Rag2-/- mice was characterized by delayed hepato-splenomegaly and unchecked parasite growth in spleen, liver and BM over a 5 month period." (PMID 34557190, 2021). "The mixed chimaeric mice developed liver pathology and splenomegaly 4 mo after the reconstitution, which, together with the data from the cross to RAG2 KO mice, indicated an important role for haematopoietic non-T, non-B cell(s) in these processes." (PMID 31694920, 2019). "Additionally, infected mice with deficiency of RAG2, T cells, or IFN-γ had splenomegaly associated with EMH, which may represent a hematopoietic pathway in response to the loss of RBCs in these mice." (PMID 28874800, 2017). "However, full lack of all types of lymphocytes utilizing Rag2 − / − Il2rg − / − mice leads to partial attenuation of cytopenia, splenomegaly, and circulating IFN-γ levels compared with Rag2 − / − mice, suggesting a smaller and redundant role for lymphocytes in this model." (PMID 36964620, 2023).